ENSG00000293680 (novel transcript)
Gene: Long non-coding RNA gene on chromosome 12 (53,953,598 to 53,966,317, reverse strand). Ensembl gene ENSG00000293680.
Gene Ontology:
Biological process: heterochromatin formation